LINC00680 (long intergenic non-protein coding RNA 680 )
Gene: Long non-coding RNA gene on chromosome 6 (57,855,890 to 57,961,501, reverse strand). Ensembl gene ENSG00000290555.
Gene Ontology:
Molecular function: triplet codon-amino acid adaptor activity
Biological process: translation
Diseases named in the same sentence as LINC00680 in open-access papers:
LINC00680 is named in the same sentence as 9 diseases in open-access papers, as found by Europe PMC text mining. Sharing a sentence is not in itself a finding about the gene and the disease. The quoted sentences say what the papers report.
glioblastoma (2 papers, 2021 to 2022). The most malignant astrocytic tumor (WHO grade IV). "Previous studies have demonstrated the oncogenic role of LINC00680 in lung cancer, hepatocellular carcinoma and glioblastoma, but the functions, molecular mechanisms, and clinical relevance of LINC00680 in ESCC remains largely unknown." (PMID 35255921, 2022). "LINC00680 is a newly identified lncRNA molecule and its role in cancer progression is largely unknown, with only one existing report suggesting LINC00680 as a tumor promoter in glioblastoma." (PMID 33499874, 2021).
breast carcinoma (1 paper, 2025). "For example, LINC00680 was found to be upregulated in docetaxel-resistant breast cancer cells and promotes resistance by sponging miR-432 to upregulate TRIM14 (which affects NF-κB signalling)—this was noted as one mechanism by which lncRNAs contribute to taxane resistance." (PMID 40806254, 2025).
Cirrhosis (1 paper, 2021). A chronic disorder of the liver in which liver tissue becomes scarred and is partially replaced by regenerative nodules and fibrotic tissue resulting in loss of liver function. "Additionally, LINC00680 expression was significantly correlated with tumor stage, tumor size, cirrhosis, and microvascular invasion." (PMID 33499874, 2021).
esophageal squamous cell carcinoma (1 paper, 2023). Esophageal squamous cell carcinoma (ESCC) is a type of esophageal carcinoma (EC) that can affect any part of the esophagus, but is usually located in the upper or middle third. "Furthermore, elevated levels of LINC00680 in esophageal squamous cell carcinoma (ESCC) were associated with large tumor size, advanced tumor stage, and poor prognosis." (PMID 37464436, 2023).
tumor (4 papers, 2021 to 2023). "Notably, LINC00680 was highly expressed, and upregulation of LINC00680 was associated with large tumor size, advanced tumor stage, and poor prognosis." (PMID 35255921, 2022). "In our study, it was found that LINC00680 was positively associated with HCC tumor size and stage, vascular invasion, and poor survival prognosis, suggesting that LINC00680 might play an important role in HCC malignancy." (PMID 33499874, 2021). "In our study, PAK6 was found to be regulated by LINC00680 through RNA-seq analysis; PAK6 was highly expressed in ESCC tumor samples; a positive relationship was revealed between the expression of LINC00680 and PAK6 in ESCC tumor samples." (PMID 35255921, 2022). "Tumor growth rate and size were dramatically reduced when LINC00680 was knocked down." (PMID 35255921, 2022). "Of significance, targeting LINC00680 by ASO was effective in suppressing tumor growth in mice." (PMID 35255921, 2022). "In addition, high expression of LINC00680 was found to be correlated with tumor size, depth of invasion, lymph node metastasis and TNM stage." (PMID 35255921, 2022). "ASOs targeting LINC00680 inhibit ESCC cells proliferation, migration and invasion in vitro and ESCC tumor formation in vivo." (PMID 37464436, 2023). "The upregulation of LINC00680 in ESCC tumor samples and its significant contribution to ESCC malignant phenotypes prompted us to exploit the potential of LINC00680 as a therapeutic target by using ASO." (PMID 35255921, 2022). "Functionally, knockdown of LINC00680 restrained ESCC cell proliferation, colony formation, migration, and invasion in vitro and inhibited tumor growth in vivo." (PMID 35255921, 2022). "Then, to explore the effects of LINC00680 on tumor growth in vivo, equal amounts of KYSE510 cells stably transfected with control shRNA or two independent shRNAs targeting LINC00680 were inoculated into BALB/c nude mice." (PMID 35255921, 2022). "We then searched for target genes that are clinically relevant (i.e. highly expressing in ESCC tumor tissues and positively correlated with poor prognosis of ESCC patients) as LINC00680, which led to the discovery of one gene named PAK6." (PMID 35255921, 2022). "Silencing of LINC00680 suppressed ESCC cell proliferation, colony formation, migration, and invasion in vitro and tumor growth in mice." (PMID 35255921, 2022).
LINC00680 also shares sentences with these, for which no sentence is quoted: cancer (3 papers); hepatocellular carcinoma (2); lung carcinoma (2); esophageal cancer (1).